MAPT (microtubule associated protein tau)
Diseases named in the same sentence as MAPT in open-access papers (continued):
Sharing a sentence is not in itself a finding about the gene and the disease.
frontotemporal dementia (continued). "SRp30c—in conjunction with YB-1 —represses the use of a downstream splice acceptor site, and was shown to regulate exon skipping in MAPT, which is associated with frontotemporal dementia." (PMID 29589097, 2018). "Other animal models have been developed which focus on tau pathology, such as the htauP301S and the PS19, which both carry the human MAPT (microtubule-associated protein tau) gene with mutations that cause fronto-temporal dementia." (PMID 28516241, 2018). "This is the case of the intronic 10+16 MAPT mutation, that causes frontotemporal dementia with parkinsonism linked to chromosome 17 (FTDP-17)." (PMID 28319892, 2017). "Mutations in MAPT have been described in frontotemporal dementia (FTD) with Parkinsonism and progressive supranuclear palsy." (PMID 27600680, 2017). "Mutations in MAPT give rise to several different clinical phenotypes, the majority of which are frontotemporal dementia, but which also include Parkinson’s disease dementia, PSP, PD, AD, LBD, CBD, PiD, AGD, and FTD/amyotrophic lateral sclerosis (ALS)." (PMID 28386764, 2017). "In June 1998, mutations in MAPT were reported in a dominantly inherited form of frontotemporal dementia and parkinsonism linked to chromosome 17q21-22." (PMID 28558799, 2017). "The intracellular accumulation of the microtubule-associated protein tau in a hyperphosphorylated form characterizes many neurodegenerative diseases, including Alzheimer’s disease (AD) and major forms of frontotemporal lobar degeneration (FTLD-Tau)." (PMID 28091722, 2017). "We evaluated olfactory dysfunction in 28 carriers of two MAPT mutations (p.N279K, p.P301L), which cause frontotemporal dementia with parkinsonism, using the University of Pennsylvania Smell Identification Test." (PMID 27855167, 2016). "Dominantly inherited mutations in MAPT were formerly associated with forms of frontotemporal dementia and parkinsonism linked to chromosome 17, first providing evidence of a link between tau dysfunction and neurodegeneration." (PMID 27147968, 2016). "Tau is encoded by a single gene MAPT, that is mutated in some cases of fronto-temporal dementia and certain other neurodegenerative diseases but somewhat surprisingly, not in AD." (PMID 27242399, 2016). "Author’s response: The section on tau has been expanded to include a discussion of MAPT mutants causing familial forms of frontotemporal lobar degeneration as suggested." (PMID 27809888, 2016). "Mutations in granulin (PGRN) and tau (MAPT), and hexanucleotide repeat expansions near the C9orf72 genes are the most prevalent genetic causes of frontotemporal lobar degeneration." (PMID 27100392, 2016). "In conclusion, the intensity and distribution of binding of the tau ligand [18F]AV‐1451 in a patient with a MAPT 10 + 16C>T mutation supports the use of this ligand in clinical studies of dementia, including frontotemporal lobar degeneration and CBS." (PMID 28097206, 2016). "Although mutations in the MAPT gene have been linked to multiple tauopathies including Alzheimer’s disease, frontotemporal dementia and progressive supranuclear palsy, knowledge regarding how tau N279K mutation causes PPND/FTDP-17 is limited." (PMID 26373282, 2015). "We report a case of frontotemporal dementia caused by a novel MAPT mutation (Q351R) with a remarkably long amnestic presentation mimicking familial Alzheimer’s disease." (PMID 23998300, 2014). "Although mutations in the tau encoding gene MAPT leads to a subtype of frontotemporal dementia and these mutations have been used to model AD tauopathy, no MAPT mutations have been found to be associated with AD." (PMID 24278307, 2013). "MAPT mutations are associated with frontotemporal dementia, frontotemporal dementia with parkinsonism, Pick's disease, progressive supranuclear palsy, progressive atypical supranuclear palsy, tauopathy, and respiratory failure." (PMID 22482072, 2012).
frontotemporal dementia (continued). "In recent years, it has been reported that mutations in the microtubule-associated protein tau gene (MAPT) cause frontotemporal dementia with parkinsonism linked to the chromosome 17." (PMID 22911817, 2012). "Known MAPT mutations lead to frontotemporal dementia and parkinsonism linked to chromosome 17 (FTDP-17), and other forms of frontotemporal lobar degeneration." (PMID 23029293, 2012). "Frontotemporal dementia (FTD) is a neurodegenerative disorder in which aggregates comprised of microtubule associated protein tau (MAPT) form in neurons." (PMID 22723997, 2012). "A key discovery in this area was the linkage of mutations in the MAPT gene (which encodes tau) on chromosome 17 to the development of a sub-type of frontotemporal dementia, FTDP17." (PMID 22654725, 2011). "Some mutations in MAPT cause frontotemporal dementia and parkinsonism linked to chromosome 17 (FTDP-17) by disrupting the normal equimolar ratio of 3R and 4R tau isoforms." (PMID 20520830, 2010). "In adult brain, these isoforms are expressed in equal amounts, but in patients with frontotemporal dementia with parkinsonism linked to Chromosome 17, mutations in the MAPT gene affects exon 10 retention such that a 2–6-fold excess of tau4R over tau3R occurs." (PMID 17604456, 2007). "It therefore appears that PGRN mutations cause FTLD-U due to a partial loss of functional PGRN, (haploinsufficiency), rather than accumulation of mutant protein characteristic of frontotemporal dementia due to MAPT mutations." (PMID 17291356, 2007). "The frontotemporal dementia-linked S320F mutation in the microtubule-associated protein tau promotes spontaneous aggregation, yet the structural basis of its amyloidogenesis remains unclear." (PMID 42078909, 2026). "Additionally, mutations in the MAPT gene can directly cause neurodegeneration, as observed in familial forms of frontotemporal lobar degeneration 6,7." (PMID 41255983, 2025). "MAPT mutations have also been associated with frontotemporal dementia with Parkinsonism." (PMID 39882510, 2025). "Furthermore, missense MAPT mutations cause frontotemporal dementia with parkinsonism, and GWAS have identified MAPT variants as risk factors for PD." (PMID 40790356, 2025). "Analysis of exome sequencing data from a 46-year-old patient with a clinical diagnosis of Parkinson’s disease revealed the presence of the pathological variant c.2013T>G (rs63750756) in the MAPT gene, which is associated with frontotemporal dementia with parkinsonism-17." (PMID 39722675, 2024). "Using reprogramming into a pluripotent state, we haveobtained and characterised in detail two lines of iPSCs –ICGi052-A and ICGi052-B – from the PBMCs of a patientwith frontotemporal dementia with parkinsonism-17, whohas a pathological genetic variant c.2013T>G (rs63750756)in the MAPT gene." (PMID 39722675, 2024). "Mutations in the TAU gene (MAPT) are causative in a subset of frontotemporal dementia cases." (PMID 37408256, 2023). "Mutations in MAPT account for around 5% of cases of frontotemporal dementia (FTD)." (PMID 37351604, 2023). "Although the overexpression of astrocyte-specific proteins, such as the glial fibrillary acidic protein (GFAP), was detected also in patients with frontotemporal lobar degeneration with MAPT mutation(s) (FTLD-MAPT), the EWCE analysis pointed towards functionally defective oligodendrocytes." (PMID 37296571, 2023). "Moreover, mutation in the copper-zinc superoxide dismutase 1 (SOD1) gene has been associated with ALS, while the alteration of MAPT genes or progranulin is linked to frontotemporal dementia (FTD)." (PMID 37242804, 2023). "Two siblings with deletion mutation ∆K281 in MAPT developed frontotemporal dementia." (PMID 37351604, 2023). "Microtubule-associated protein tau (MAPT) gene mutations (>100), also present in some patients with AD, may cause brain tauopathies (e.g., frontotemporal dementia, Pick’s disease)." (PMID 35330211, 2022).
frontotemporal dementia (continued). "10+16 MAPT mutation induces an increase in 4R tau and is causative of frontotemporal dementia." (PMID 34057756, 2022). "Mutations in MAPT (microtubule-associated protein tau) cause frontotemporal dementia (FTD)." (PMID 34426604, 2021). "In patients with pathologically confirmed FTD, the hippocampus has been shown to be significantly smaller in Pick's disease (33% volume difference from controls) as well as in FTDP-17 (i.e. MAPT mutations: 43%) and TDP-43 type C cases (usually those with svPPA: 33%)." (PMID 34458729, 2021). "Thus, the relative overproduction of either 3R or 4R τ, as a result of coding region or intronic mutations in MAPT, gives rise to dominantly inherited frontotemporal dementias." (PMID 34846514, 2021). "Mutations in MAPT, the τ gene, give rise to familial forms of frontotemporal dementia." (PMID 34846514, 2021). "Conversely the MAPT loci encodes tau, aggregates of which are found in a range of neurodegenerative diseases such as Alzheimer’s disease, frontotemporal dementia and progressive supranuclear palsy, suggesting the involvement of other pathways in PD pathogenesis." (PMID 34208795, 2021). "Also, mutations in the MAPT gene encoding for Tau lead to frontotemporal dementia with Parkinsonism 171,2." (PMID 32427887, 2020). "MAPT mutations were the first discovered genetic cause of frontotemporal dementia (FTD) in 1998." (PMID 31870644, 2020). "Importantly, mutation in the alpha-synuclein gene (SNCA) leads to Parkinson’s disease, and the Tau gene FTDP-17 with 10 + 16 MAPT mutation is shown to be linked to a familial form of frontotemporal dementia." (PMID 32629809, 2020). "Mutations in the microtubule-associated protein tau (MAPT) gene cause different familial forms of frontotemporal lobar degeneration (FTLD) including Pick’s disease (PiD), progressive supranuclear palsy (PSP), corticobasal degeneration (CBD), and globular glial tauopathy (GGT)." (PMID 32571418, 2020). "The neuropathology of MAPT-mutation syndromes ischaracterized by frontotemporal lobar degeneration (FTLD), a neurodegenerativeprocess involving neuronal loss and gliosis of the frontal and temporal brainregions, in the presence of hyperphosphorylated tau inclusions." (PMID 32973976, 2020). "Mutations in the gene encoding the microtubule-associated protein TAU (MAPT) are a common cause of frontotemporal dementia (FTD), a group of neurodegenerative diseases characterized by progressive nerve cell loss in the frontal lobes and the temporal lobes in the brain." (PMID 31398826, 2019). "These simple-to-use and reproducible scales may be useful tools in the clinical setting for the discrimination of different mutations of frontotemporal dementia, and they may even help to identify atrophy prior to onset in those with MAPT mutations." (PMID 29793546, 2018). "MAPT mutations cause neurodegenerative diseases such as frontotemporal dementia but, strikingly, patients with the same mutation may have different clinical phenotypes." (PMID 28978354, 2017). "Here, we demonstrate that binding of the tau radioligand [18F]AV‐1451 was significantly abnormal in both magnitude and distribution in a patient with familial frontotemporal dementia due to a MAPT 10 + 16C>T gene mutation, recapitulating the pattern of neuropathology seen in her father." (PMID 28097206, 2016). "FTD (frontotemporal dementia) neurons differentiated from induced pluripotent stem cells (iPSCs) from individuals with FTD-associated MAPT mutations show activation of the UPR; a transcriptome analysis of these cells exhibited disease-associated gene expression profiles." (PMID 27304053, 2016). "Neurofibrillary tangles comprised of a hyperphosphorylated form of the microtubule-associated protein tau, are characteristic not only of AD but also of other tauopathies including an autosomal dominant form of frontotemporal lobar degeneration (FTLD), named FTDL-17 after the affected chromosome." (PMID 27809888, 2016).
frontotemporal dementia (continued). "In addition, mutations in the frontotemporal lobar degeneration (FTLD) genes – the microtubule-associated protein tau (MAPT), granulin (GRN) – have also been found to be associated with clinical AD." (PMID 25333068, 2014). "FTD with tau-positive inclusions: This includes classic Pick’s disease, Progressive Supranuclear Palsy, Corticobasal degeneration, argyrophilic grain disease, and patients with mutation of the Microtubule-associated protein tau (MAPT) gene on chromosome 17 (FTDP-17)." (PMID 21369422, 2010). "Using CRISPR/CRISPR‐associated protein 9 (Cas9) genome editing, we further engineered frontotemporal dementia (FTD)‐causing MAPT mutations (P301L and R406W)." (PMID 40219788, 2025). "Additionally, we explored two of the three main genetic mutations associated with frontotemporal dementia (FTD)—those in the Microtubule-Associated Protein tau (MAPT) and Progranulin (GRN) genes—as FTD is a neurodegenerative condition that often affects younger populations." (PMID 40725212, 2025). "In neurodegenerative diseases, notably, frontotemporal dementia (FTD) and Parkinson’s disease (PD), genetic mutations—including MAPT, LRRK2, PINK1, PRKN, and SNCA—have been reported to alter Nrf2 signaling, both in vitro and in vivo." (PMID 41154499, 2025). "Similar effects can be achieved in transgenic models expressing frontotemporal dementia (FTD)-associated MAPT mutations." (PMID 39272998, 2024). "Human tau, encoded by the MAPT gene, is a protein that normally binds tubulin and facilitates microtubule stabilization; however, it can pathologically aggregate inside neurons and form neurofibrillary tangles in Alzheimer’s disease (AD) and many cases of frontotemporal dementia (FTD)." (PMID 38540368, 2024). "Up to 15–20% of hereditary forms of frontotemporal dementia (FTD) are due to microtubule-associated protein tau (MAPT) mutations, resulting in hyperphosphorylated neuronal and glial inclusions." (PMID 38592608, 2024). "Cognitive loss is much more robustly correlated with MAPT based NFTs pathology, and mutations in MAPT are sufficient to cause dementia (frontotemporal dementia, FTD)." (PMID 37292629, 2023). "Based on familial cases of frontotemporal dementia with parkinsonism linked to chromosome 17, Pick's diseases, corticobasal degeneration, and progressive supranuclear palsy, disease-causing mutations in the MAPT (MAP tau) gene lead to heterogeneous molecular consequences." (PMID 35218773, 2022). "Clinical and genetic overlap exists with frontotemporal dementia (FTD), which is caused by mutations in C9orf72, MAPT, GRN, TARDPB, VCP, as well as other genes." (PMID 35493319, 2022). "MSTD was soon understood to belong to a group of familial tauopathies associated with MAPT gene mutations, collectively referred to as frontotemporal dementia with parkinsonism linked to chromosome 17 (FTDP-17)." (PMID 35806324, 2022). "We report in vivo patterns of neuroinflammation and abnormal protein aggregation in seven cases of familial frontotemporal dementia (FTD) with mutations in MAPT, GRN and C9orf72 genes." (PMID 33122395, 2021). "Mutations in microtubule-associated protein tau (MAPT) result in the alteration of protein structure and the availability of different tau isoforms, which later cause impairments in the microtubule assembly and axonal transport, and eventually lead to frontotemporal dementia." (PMID 32466129, 2020). "Mutations in the microtubule-associated protein tau (MAPT) gene are known to cause familial frontotemporal dementia (FTD)." (PMID 31543469, 2019). "The MAPT p.A152T variant has been associated with other neurodegenerative diseases including AD and frontotemporal dementia (FTD)." (PMID 27094865, 2016). "In this study we used a C.elegans model to examine the toxicity of a rare mutation in the MAPT gene (A152TMAPT) that was recently discovered as a risk factor for frontotemporal dementia spectrum disorders (FTD, PSP, CBD, AD, and others)." (PMID 27118310, 2016).
frontotemporal dementia (continued). "Progressive supranuclear palsy (PSP) and frontotemporal dementia (FTD) are two neurodegenerative diseases linked, at the pathologic and genetic level, to the microtubule associated protein tau." (PMID 24603599, 2014). "Mutations in progranulin (GRN) and in microtubule associated protein tau (MAPT) are an established cause of familial frontotemporal dementia (FTD)." (PMID 22312439, 2012). "Since then, >50 genetic mutations and variants in MAPT have been associated with familial forms of FTD, including Pick's disease (PiD), progressive supranuclear palsy (PSP), and corticobasal degeneration (CBD)." (PMID 40113250, 2025). "Mutations in the human tau (MAPT) gene cause familial forms of FTD1–3, which can manifest as progressive supranuclear palsy, corticobasal syndrome, Pick’s disease and globular glial tauopathy." (PMID 39719507, 2025). "While pathogenic MAPT mutations are well-characterized within exons 9–13, and most GRN CNVs are known to cause haploinsufficiency in frontotemporal dementia, the specific roles of CNVs in MAPT exon 8 and GRN exon 6 remain poorly defined." (PMID 40725212, 2025). "MAPT variants are also linked with frontotemporal dementia (FTD)." (PMID 40362170, 2025). "A recent report from the Genetic Frontotemporal Dementia Initiative (GENFI) used multiplexed assays to measure CSF and plasma levels of complement components and activation products in FTD cases with known genetic mutations in MAPT, C9ORF or GRN at different stages of the disease." (PMID 38505993, 2024). "The mutations on microtubule associated protein tau (MAPT) gene manifest clinically with behavioural frontotemporal dementia (FTD), parkinsonism, such as progressive supranuclear palsy and corticobasal degeneration, and rarely with amyotrophic lateral sclerosis (ALS)." (PMID 37730935, 2024). "In this work, we have obtained, characterised and certifiedtwo lines of iPSCs from a patient with a pathological geneticvariant of MAPT:c.2013T>G (rs63750756, p.N279K), whichleads to the development of frontotemporal dementia withparkinsonism-17." (PMID 39722675, 2024). "MAPT p.Asn596Lys has been reported in patients diagnosed with pallido‐ponto‐nigral degeneration and has been confirmed as a pathogenic mutation." (PMID 36879366, 2023). "An intriguing finding in patients with frontotemporal dementia (FTD) is the presence of partial deletions in the MAPT gene, leading to truncated tau proteins that lack the first microtubule-binding repeat." (PMID 37927337, 2023). "A well-characterized example is frontotemporal dementia and Parkinsonism linked to chromosome 17 (FDTP-17), which is caused by mutations in the microtubule-associated protein tau (MAPT) gene encoding the tau protein." (PMID 37909333, 2023). "Genetic mutations in TARDBP, C9orf72, MAPT and SOD1 have been used to classify frontotemporal dementia and amyotrophic lateral sclerosis." (PMID 35202463, 2022). "Rather, a clinically distinct familial disorder, frontotemporal dementia (FTD) with parkinsonism, was mapped to dominant mutations in MAPT." (PMID 34718566, 2022). "Here we investigated the proteomic signatures of frontal and temporal cortex from brains with frontotemporal dementia due to GRN and MAPT mutations to identify the key cell types and molecular pathways in their pathophysiology." (PMID 35799292, 2022). "Frontotemporal dementia (FTD) is the second cause of dementia with an age of onset < 65, and its most common mutations are in GRN, C9orf72, and MAPT genes." (PMID 35145377, 2022). "Genetic causes of FTLD, including MAPT, PGRN and C9orf72 genes, should be excluded; C9orf72 is particularly often related to behavioural variant of frontotemporal dementia, with the presence of motor neuron disease symptoms, which are absent in PSP-F." (PMID 35221993, 2022). "Earlier research has shown that multiple pathogenic mutations in MAPT are associated with diverse FTD syndromes, and, contribute to frontotemporal lobar degeneration." (PMID 34575885, 2021).